AR (androgen receptor)
Diseases named in the same sentence as AR in open-access papers (continued):
Sharing a sentence is not in itself a finding about the gene and the disease.
prostate carcinoma (continued). "The mechanism controlling prostate cancer (PC) invasion is debated, and even unclear appears the role of the androgen receptor (AR) in this process." (PMID 35011576, 2021). "Paclitaxel treatment of the prostate cancer cell line CRPC (castration-resistant prostate cancer) inhibits androgen receptor (AR) activity." (PMID 34830812, 2021). "The major disease where the AR plays a key role is prostate cancer, the second most commonly diagnosed malignancy in men worldwide and the fifth leading cause of cancer-related death." (PMID 33634124, 2021). "Comparative analysis identified sub-network cluster profiles for AR interaction that correlated with prostate cancer progression and outcome." (PMID 34638309, 2021). "In prostate cancer, the activated EHZ2 pathway is associated with resistance to AR-targeted therapy." (PMID 35186711, 2021). "The authors conclude that PIM1 phosphorylation of these substrates regulates the AR transcriptome in prostate cancer cells." (PMID 34697370, 2021). "Bergamottin, a potent CYP3A inhibitor blocks prostate cancer cell growth by inhibiting AR expression, nuclear localization, and PSA production." (PMID 34570813, 2021). "In order to explore why AR/AR-V7-positive prostate cancer cells are more sensitive to nobiletin, western blot and immunofluorescence assays were performed." (PMID 34548474, 2021). "VCaP cells, a prostate cancer cell line with AR amplification, displayed the highest level of total NDRG1 and NDRG1 pS330, consistent with our findings that NDRG1 expression and phosphorylation are androgen-regulated." (PMID 33398037, 2021). "AR, which is a member of the nuclear receptor superfamily, contributes to the development of both normal prostate and prostate cancer." (PMID 34944692, 2021). "LncRNA LBCS functions as a novel AR translational regulator that suppresses castration resistance of prostate cancer by interacting with hnRNPK." (PMID 34697900, 2021). "In comparison with clinically approved AR antagonists (such as ENZ, etc.), ARD-61 exhibited stronger anti-proliferative and pro-apoptotic effects and attenuated the expression of AR target genes in prostate cancer cells in vivo and in vitro." (PMID 34488823, 2021). "Androgen receptor (AR) signaling is important in prostate cancer progression, and therapies that target this pathway have been the mainstay of treatment for advanced disease for over 70 years." (PMID 34322653, 2021). "Radiotherapy has been shown to induce Androgen receptor expression in prostate cancer cells, and androgen deprivation therapy sensitizes cancer cells to radiotherapy." (PMID 34778082, 2021). "In this review, we will discuss relatively understudied aspects of ER and AR activity in regulating protein synthesis as well as the potential of targeting mRNA translation in breast and prostate cancer." (PMID 34209750, 2021). "Recent studies have found that the upregulation of MAZ promotes the proliferation and metastasis of prostate cancer by promoting androgen receptor expression." (PMID 34183010, 2021). "These hormones can stimulate prostate cancer proliferation through activation of the FOXO1 subunit of the androgen receptor." (PMID 33921222, 2021). "Imaging mass cytometry (IMC) revealed that 49% of cytokeratin (CK)-positive LEVs and CTCs were EpCAM-negative, while frequently carrying prostate cancer tumor markers including AR, PSA, and PSMA." (PMID 33801459, 2021). "The treatment landscape of prostate cancer has changed dramatically following the advent of novel systemic therapies, most of which target the androgen receptor (AR)." (PMID 34884545, 2021). "Prostate-specific antigen (PSA, kallikrein-related peptidase 3, KLK3) is another interesting target for prostate cancer radiotheranostics downstream of the AR." (PMID 34298682, 2021).
prostate carcinoma (continued). "In hormone-dependent tumors such as prostate carcinoma or hormone receptor-positive breast cancer, anti-hormonal therapies, for example, by inhibiting AR or ER, are already an integral part of therapy." (PMID 34768978, 2021). "We previously reported that dietary white button mushroom (WBM) antagonized dihydrotestosterone (DHT)-induced androgen receptor (AR) activation and reduced myeloid-derived suppressor cells (MDSCs) in prostate cancer animal models and patients." (PMID 33791688, 2021). "Much attention has lately been given to DiMC due to its potency against various cancer cell lines in many cases, such as the ability to serve as an androgen receptor antagonist in human prostate cancer cells in vivo." (PMID 34295247, 2021). "Androgens and androgen receptor (AR), a hormone-activated transcription factor (TF), are key factors driving the development and progression of prostate cancer (PCa)." (PMID 34127815, 2021). "Additional reports also show that loss of PTEN function can facilitate the progression to androgen independent prostate cancer by enabling AR activation." (PMID 34439133, 2021). "Taken together, our results demonstrate that PRPF6 is involved in enhancement of oncogenic AR signaling, which provides an insight to potential therapeutic strategies for prostate cancer, especially for CRPC." (PMID 33390843, 2021). "Accordingly, KDM4B is an ideal candidate target for advanced prostate cancer given its dual function to coactive c-Myc and AR." (PMID 34335964, 2021). "The development of compounds which block AR activation in prostate cancer is a continuous process that has led to improvements in clinical care." (PMID 34204596, 2021). "Consistently, KLF5 promoted the expression of the basal cytokeratin CK5 in AR-positive prostate cancer cells, which supports a role for KLF5 in lineage plasticity." (PMID 34737261, 2021). "Our finding that PARP7 is regulated by AR signaling both transcriptionally and post-transcriptionally in prostate cancer cells suggests the dosage of PARP7 protein is subject to tight regulation." (PMID 33572475, 2021). "AKR1C3, a crucial androgenic enzyme, can reprogram AR signaling in advanced prostate cancer and is involved in the production of aromatase substrates in breast cancer." (PMID 34336641, 2021). "FOXA1 is known as a key pioneer transcription factor for nuclear receptors such as estrogen receptor (ER) and androgen receptor (AR) in breast and prostate cancers, respectively." (PMID 33666335, 2021). "Similar to our study, previous literature has reported two class hybrid molecules of AR antagonist and pan-HDACi for treating prostate cancer." (PMID 33621955, 2021). "Since p300-mediates expression of SLCO1B3, we first examined the effect of antiandrogens on SLCO1B3 expression in two well characterized AR-positive prostate cancer cell lines (22Rv1 & LNCaP)." (PMID 34031488, 2021). "Conversely, in vitro studies have shown an AR-mediated activation of mTOR independently of PI3K-Akt stimulation in prostate cancer cells stimulated with Dihydrotestosterone (DHT)." (PMID 35011901, 2021). "Taken together, we identified AR relating sense eRNAs and antisense eRNAs regulated sense mRNA and antisense ncRNA in prostate cancer cells." (PMID 33408781, 2021). "This shows a definitive role of the β-catenin pathway and its cross-talk with androgen receptor in the progression of prostate cancer." (PMID 35201496, 2021). "Significantly increased expression of Skp2, AR, and Slug, along with lower expression of E-cadherin, was also observed in primary prostate cancer in patients who already had lymph node metastases." (PMID 33799604, 2021). "We further assessed both agonist and antagonist activity of AR signaling in AR-dependent VCaP prostate cancer cell line." (PMID 33621955, 2021). "Transfection of β‐catenin in prostate cancer cells augmented the ligand‐dependent transcription downstream of AR." (PMID 33085215, 2021).
prostate carcinoma (continued). "Prostate cancer (PCa) cells are able to increase GR signaling during anti-androgen therapy and thereby circumvent androgen receptor (AR) blockade and cell death." (PMID 34412644, 2021). "In recent years, anti-AR resistant prostate cancer cases with neuroendocrinal features (also known as NEPC) have emerged with an aggressive phenotype in about 17% of CRPC cases." (PMID 34572596, 2021). "In conclusion, taken together, our data indicate that resistance to short-term AR signaling inhibition in prostate cancer is driven by molecular mechanisms that are distinct from those underpinning progressive castration-resistant outgrowth." (PMID 34322653, 2021). "Western blotting of androgen receptor (AR)-proficient and -deficient prostate lines confirmed upregulation of ARF6 and IQSEC1 protein expression in metastatic prostate cancer cell lines (LNCaP, VCaP, DU145, PC3)." (PMID 33712589, 2021). "It has been shown that AR mutations found in prostate cancer patients were related to their affinity for SRC-3, and SRC-3 promoted the development of prostate cancer through AR-dependent and -independent signaling." (PMID 33946224, 2021). "The androgen receptor is an important therapeutic target that plays a pivotal role in mediating several diseases, including prostate cancer and male infertility." (PMID 33572727, 2021). "Further evaluation of their (including their optically pure versions) promising potency and selectivity in other AR-positive prostate cancer cell lines, as well as their AR modulating capability, are in progress and will be reported in due course." (PMID 34770829, 2021). "ASC9, the enol isomer of DiMC, is a recently developed anti-AR agent which effectively suppresses castration-resistant prostate cancer cell proliferation and invasion." (PMID 34295247, 2021). "On the other hand, PAQR8 expression was negatively regulated by AR signaling and correlated with NEPC progression after ADT/AR antagonist treatment in prostate cancers." (PMID 34572596, 2021). "Previous studies showed that RANBP10 was overexpressed in prostate cancer cells and was responsible for androgen receptor (AR) activation." (PMID 34671019, 2021). "It has been considered that aberrant expression of AR-FL/AR-Vs co-regulators lead to prostate cancer as well as CRPC via the abnormal function of co-regulators on modulation of AR transcriptional network 11-14." (PMID 33390843, 2021). "Prostate cancer becomes resistant to treatments targeting oncogenic androgen receptor (AR) via coordinated activity of multiple adaptive responses." (PMID 33709547, 2021). "There are reports showing the difference in drug response between AR expressing and non‐expressing prostate cancer cells." (PMID 34434533, 2021). "Androgen receptor regulates the expression of multiple genes and is highly effective for metastatic prostate cancer treatment." (PMID 33219721, 2021). "In prostate cancer, androgen receptor signalling promotes glutamine metabolism, which is also involved in cholesterol homeostasis." (PMID 34638444, 2021). "RNF6 atypically polyubiquitinates at Lys‐6 and Lys‐277 and facilitates transcriptional activity of the androgen receptor (AR) because of its overexpression in prostate cancer." (PMID 34081837, 2021). "From this, we proposed that upregulation of MED19 in prostate cancer cells drives AR activity and androgen independence." (PMID 33513133, 2021). "Another current strategy to treat prostate cancer is the use of AR competitive antagonists alone or in combination with anti-metastatic drugs or immunotherapy." (PMID 33712665, 2021). "Galeterone, a potent dual inhibitor of CYP17 and AR, is more effective than castration for treating prostate cancer in tumor xenograft model and is also effective in phase I/II clinical studies." (PMID 33621955, 2021). "PIM1-mediated AR serine 213 phosphorylation (pS213) differentially impacts AR target gene expression and is correlated with prostate cancer recurrence." (PMID 33398037, 2021).
prostate carcinoma (continued). "Current endocrine therapy for prostate cancer (PCa) mainly inhibits androgen/androgen receptor (AR) signaling." (PMID 33391508, 2021). "Collectively, this work provides new insight into the dysregulated metabolism of prostate cancer and provides impetus for further investigation of co-targeting AR and the PPP as a novel therapeutic strategy." (PMID 34382934, 2021). "Despite advances in the development of highly effective androgen receptor (AR)-directed therapies for the treatment of men with advanced prostate cancer, acquired resistance to such therapies frequently ensues." (PMID 34099734, 2021). "As such, androgens and the key mediator of their functions, androgen receptor (AR), have a leading role in several diseases such as androgen insensitivity syndrome and prostate cancer." (PMID 33634124, 2021). "The expression of common prostate cancer biomarkers, including AR, AMACR, PSA, PSMA, ERG, and neuroendocrine markers (synaptophysin, chromogranin A and CD56) were continually assessed across PDX generations." (PMID 34413304, 2021). "AR plays a fundamental role in prostate cancer development by ensuring cell survival and proliferation but also migration and invasion, which are hallmarks for human cancer." (PMID 34638258, 2021). "The Androgen Receptor (AR) is a protein involved in reproduction, brain development, prostate cancer, androgen insensitivity syndromes, spinal and bulbar muscular atrophy, acne, and alopecia." (PMID 33652992, 2021). "Our current analyses reveal that AR activated by R1881 or AR-V7 induced by Dox drive the production of alternative mRNA isoforms in prostate cancer cell lines." (PMID 33446905, 2021). "The interactome research relevant for prostate cancer is so far concentrated on AR and certain other transcription factors, and is thus closely connected to events on chromatin." (PMID 34638309, 2021). "Normal maintenance and development of the prostate is dependent on androgens and androgen receptor (AR) signaling, which also plays a key driving role in the development and progression of prostate cancer." (PMID 34367984, 2021). "Some studies have reported that the apoptotic effects of curcumin on prostate cancer cells are due to its inhibitory effects on androgen synthesis and androgen receptor expression." (PMID 35855104, 2021). "Ang-II has the ability to stimulate androgen receptor (AR) expression in prostate cancer cells via the angiotensin-II type-1 receptor (AT1R)." (PMID 34943797, 2021). "Our observation that bergamottin, a natural furanocoumarin found in grapefruit juice, also blocks the androgen receptor expression and activation is very significant as it can be used as a dietary supplement to prevent prostate cancer growth." (PMID 34570813, 2021). "We recently demonstrated that the AR forms these liquid-like foci in prostate cancer models upon androgen stimulation that correlate with its transcriptional activity." (PMID 34298700, 2021). "ARV-110 inhibited the synthesis of prostate-specific antigen (PSA) and AR-dependent prostate cancer cell proliferation by inducing apoptosis." (PMID 36046114, 2021). "It has always been believed that reducing serum androgen levels in prostate cancer patients by surgery or chemical methods can completely inhibit the AR signaling pathway and inhibit the progression of prostate cancer." (PMID 34150618, 2021). "Surprisingly, AR, which represents the major driver in prostate cancer proliferation, resulted among the genes that were significantly downregulated." (PMID 34966687, 2021). "Our preliminary WST cell proliferation assay data exhibit that 5,7,20-O-trimethylsilybin and four 3-O-carbamoyl-5,7,20-O-trimethylsilybins bear high selectivity and promising potency towards the AR-positive LNCaP prostate cancer cell line." (PMID 34770829, 2021).
prostate carcinoma (continued). "Despite significant progress in anti-androgen therapies for CRPC, as a second-generation AR antagonist, enzalutamide has been widely used in treatment of advanced prostate cancer." (PMID 34776951, 2021). "To test this, we investigated the distribution of AR sites in previously published ChIP‐seq datasets from benign prostate tissues, primary prostate cancers and cell lines (LNCaP and VCaP and in mCRPC patient‐derived xenografts (PDX)." (PMID 33576154, 2021). "The first all-small molecule PROTAC utilizes nutlin to recruit the E3 ligase MDM2 to degrade androgen receptor (AR) in prostate cancer cells." (PMID 35006464, 2021). "BMI1 also possesses functions independent of CDKN2A repression, including the regulation of genes involved in differentiation and cell contact inhibition in Ewing sarcoma and androgen receptor expression in prostate cancer." (PMID 33523558, 2021). "AR plays an essential role in prostate cancer and modulates the expression of cell cycle-, survival-, and growth-regulating proteins." (PMID 34681618, 2021). "Enzalutamide is a potent androgen receptor (AR) antagonist that competitively inhibits the binding of androgens to the AR, thereby blocking AR signaling and subsequently the proliferation of prostate cancer cells." (PMID 34944897, 2021). "For example, resveratrol regulates the AKT and ERK pathways through androgen receptor-independent mechanisms in prostate cancer cells and also inhibits AR pathways in androgen receptor-dependent prostate cancer cells." (PMID 34298624, 2021). "Despite biochemical recurrence in patients treated with definitive first-line ADT, the androgen receptor (AR) remains an important driver of prostate cancer and, thus, the primary target of pharmacologic intervention." (PMID 33558665, 2021). "ELK1 is an ETS transcription factor and AR co-regulator that promotes growth in prostate cancer cells and regulates ligand-independent recruitment of AR to chromatin through interaction with the AR NTD." (PMID 33513133, 2021). "In summary, our study revealed that huaier extract is effective in both hormone-sensitive and castration-resistant prostate cancer via targeting AR-FL and AR-V7 signaling pathways." (PMID 33708629, 2021). "Several AR-independent mechanisms involving signaling pathways able to bypass the AR, or the existence of AR-negative prostate cancer stem cells, ultimately leading to the development of CRPC5 have also been identified." (PMID 34290270, 2021). "Further, we noted earlier that activation of the AR in human prostate cancer cell line PC-3 stimulated the expression of IFI16 PYHIN proteins." (PMID 33923931, 2021). "Several mechanisms have been proposed in these studies to explain the tumorigenicity effect of DHX15, such as the co-activation of the androgen receptor in prostate cancer and the transcriptional activation of NF-kB in leukemia cells." (PMID 34654883, 2021). "As we all know, the androgen receptor (AR) signaling plays an important role in the progression of prostate cancer." (PMID 33849550, 2021). "Elevated UGT2B17 expression levels enhances the progression of castration-resistant prostate cancer by promoting independent androgen receptor signaling and cancer cell mitosis." (PMID 33619235, 2021). "Androgen signaling via the androgen receptor (AR) is involved in normal prostate development and prostate cancer progression." (PMID 34680521, 2021). "In PRAD, the stromal cells express the androgen receptor (AR), which is the main driver of prostate cancer pathogenesis and progression." (PMID 34133324, 2021). "The stronger inhibition of AR signaling through ARSi in recent years has led to an increase of metastatic prostate cancers that de-differentiate into AR-negative disease and consequentially no longer respond to the inhibition of the AR signaling axis." (PMID 33420371, 2021).